CDKN2A (cyclin dependent kinase inhibitor 2A)
Diseases named in the same sentence as CDKN2A in open-access papers (continued):
Sharing a sentence is not in itself a finding about the gene and the disease.
astrocytomas (199 papers, 1997 to 2026). "Worse survival in patients with astrocytoma and CDKN2A/B hemizygous loss was observed, specifically in WHO grade 2, but this prognostic effect disappeared when adjusting for clinical factors." (PMID 42109834, 2026). "Grade 4 IDH1/2-mutant astrocytomas with intact CDKN2A/B and focal amplifications showed decreased median survival at 55.9 months while grade 4 tumors with loss of CDKN2A/B (hemizygous: 31.9 months, homozygous: 32.5 months) fared the worst." (PMID 39584448, 2025). "On univariate analysis, IDH1/2-mutant astrocytoma patients with CDKN2A/B hemizygous loss exhibited significantly shorter survival than their intact CDKN2A/B counterparts within each grade." (PMID 39584448, 2025). "CDKN2A/B homozygous-loss associates with worse survival in IDH1/2-mutant astrocytomas (IDHmut-astrocytomas), the presence of which denotes a grade 4 tumor independent of histologic features." (PMID 39584448, 2025). "Intermediate risk patients with grade 3 astrocytomas and CDKN2A/B hemizygous loss, intact CDKN2A/B but focal amplifications and grade 4 patients with intact CDKN2A/B and no focal amplifications have median OS of 80.4, 88.7 and 91.5 months, respectively." (PMID 40949165, 2025). "Combining CDKN2A/B hemizygous-loss and focal gene amplifications reveals a group of IDHmut-astrocytoma patients with an intermediate prognosis, refining IDHmut-astrocytoma classification." (PMID 39584448, 2025). "Next, we evaluated an IDH-mutant astrocytoma with partial loss of CDKN2A/B (based on methylation-array data) demonstrating the highest prediction score for heterozygous deletion of CDKN2A/B across all four biopsies." (PMID 39880907, 2025). "Marked contrast enhancement in grade 4 astrocytoma is associated with the presence of homozygous CDKN2A deletion, although with low sensitivity (80%) and specificity (58%)." (PMID 40949165, 2025). "Presence of a CDKN2A/CDKN2B homozygous deletion is associated with particularly poor outcome of IDH-mutant astrocytoma patients, even within the group of patients with CNS WHO grade 4 tumors." (PMID 38183430, 2024). "This new definition is based on previous studies in which CDKN2A/B-HD was found to be associated with poor prognosis among astrocytoma, IDH-mutant." (PMID 39117984, 2024). "The presence of > 33% and > 50% T2-FLAIR mismatch was observed in 23 cases (74.2%) and 14 cases (45.2%), respectively, and was associated with CDKN2A-intact astrocytoma (p = 0.0001, 0.0482)." (PMID 39117984, 2024). "If a molecular definition is accepted (i.e. a typical methylation class, a MAPK alteration and CDKN2A/B loss), the morphological spectrum is much wider and needs to be considered in the context of any moderately cellular astrocytoma." (PMID 39294363, 2024). "We have previously identified a family with a history of early-onset melanoma and astrocytoma with an allelic loss of function of CDKN2A p14ARF-specific transcript mutation (c.193G>A; p.G65S) and the ATM Ser49Cys allele." (PMID 38338943, 2024). "The presence of > 33% and > 50% T2-FLAIR mismatch was associated with CDKN2A-intact astrocytoma (p = 0.0003, 0.0482)." (PMID 39117984, 2024). "The ATM Ser49Cys variant was suggested from our previous familial melanoma and astrocytoma study as being a modifier of impact of a CDKN2A p14ARF variant, associating with an earlier age of onset." (PMID 38338943, 2024).
astrocytomas (continued). "CDKN2A HD was associated with a dismal outcome in IDH-mutant astrocytomas (p < 0.0001 for PFS and p = 0.004 for OS) in both univariate and multivariate analyses." (PMID 37504251, 2023). "CDKN2A/B HD are identified in approximately 22% of IDH-mutant astrocytomas and are thought to lead to the loss of cell cycle control and promote cell proliferation." (PMID 37504251, 2023). "CDKN2A/B homozygous deletion has only recently been added to the diagnostic paradigm for IDH[isocitrate dehydrogenase]-mutant astrocytomas; thus, associated radiogenomic literature is sparse." (PMID 37316586, 2023). "Another study demonstrated that combination of CDK4 amplification and/or CDKN2A deletion, and chromosome 14 loss conferred poor prognosis in astrocytoma, IDH-mutant." (PMID 38012788, 2023). "Several retrospective studies have shown CDKN2A/B HD is associated with decreased survival among IDH-mutant astrocytomas." (PMID 37504251, 2023). "In 2021, the homozygous deletion of cyclin-dependent kinase inhibitor 2A/B (CDKN2A/B) was introduced as another diagnostic hallmark to identify IDHmut astrocytomas with a worse clinical outcome and hence WHO grade 4 classification." (PMID 37173969, 2023). "In a high-grade astrocytic tumor with IDH mutation, the diagnosis of IDH-mutated astrocytoma WHO grade 4 can be made if homozygous deletions of CDKN2A/B are confirmed." (PMID 37626776, 2023). "In IDH-mutant astrocytomas, the presence of homozygous deletion of CDKN2A is associated with poor outcome and an expected median overall survival of only 3 years." (PMID 37138345, 2023). "Loss of CDKN2A/B has been identified in soft tissue sarcomas, B‐cell non‐Hodgkin lymphoma, and astrocytoma." (PMID 35639915, 2022). "Of 106 cases of IDH-wildtype infiltrating astrocytoma with copy number data for CDKN2A, loss was seen in 67 cases (63.2%)." (PMID 36397144, 2022). "Cyclin-dependent kinase inhibitor 2A/B (CDKN2A/B) homozygous deletion in IDH1/2 mutant astrocytoma associates with a poor prognosis, similar to WHO IV tumors." (PMID 34540693, 2021). "We also observed two major clusters with significant difference in CDKN2A/B deletion in IDH mutant astrocytoma cohort associated with high proportion of CD8 T, B-cell, and endothelial cells." (PMID 34496929, 2021). "Of these, the CDKN2A homozygous deletion has been proposed as a strong prognostic factor in IDH-mutated astrocytomas." (PMID 33228806, 2020). "Features typical of astrocytomas, such as copy-neutral loss of heterozygosity at 17p and the deletion of the cyclin-dependent kinase inhibitor 2A (CDKN2A) gene, were also detected in both cases." (PMID 26865861, 2016). "CDKN2A has a high frequency of homozygous deletions in high-grade astrocytomas, while mutations and promoter methylation of p14ARF or p16INK4A have a lesser importance in these tumors." (PMID 22389839, 2012). "Similarly, hemizygous loss of CDKN2A/B is associated with reduced survival in IDH1/2 mutant astrocytomas." (PMID 40949165, 2025). "Furthermore, homozygous CDKN2A deletion has been linked to the recurrence and progression of IDHmut astrocytomas and is currently a determining criterion for a grade 4 diagnosis, irrespective of low-grade tissue histology." (PMID 37932833, 2023). "G-CIMP-low IDH-mutant astrocytomas are associated with abnormalities in CDKN2A." (PMID 37504251, 2023).
astrocytomas (continued). "p16, encoded by the CDKN2A gene, is a major tumor suppressor protein, highly expressed in senescent cells in in vitro models and inactivated in a variety of human cancers, including 30 to 70% of pediatric or adult high-grade astrocytomas." (PMID 36831610, 2023). "The only exceptions are also the presence of CDKN2A/B homozygous deletion for IDHm astrocytoma, and of TERT promoter mutation, EGFR gene amplification, and chromosome 7 gain/chromosome 10 loss for IDH wild-type diffuse astrocytomas, which classify them as grade IV, which were missing in our study." (PMID 37534252, 2023). "Variability in CDKN2A/B copy number alteration indicates that there is a risk of sampling bias that may lead to misclassification of tumor grade in IDH-mutant astrocytomas." (PMID 35701666, 2022). "In the present study, a correlation between PDGFRA gain/amplification and CDKN2A homozygous loss was seen, and might imply that astrocytoma with alteration of PDGFR is associated with “RTK I” GBM." (PMID 34257410, 2021). "Also, for the group of IDH-mutant astrocytomas a reworked grading system was proposed, acknowledging homozygous loss of CDKN2A as a main factor of unfavorable prognosis." (PMID 32758285, 2020). "Taken together, these results indicate that loss of CDKN2A/B may provide adult IDH-wildtype astrocytomas with a reliable means for senescence bypass." (PMID 29616301, 2018). "It was demonstrated that expression of BRAFV600E may cause transformation when combined with loss of CDKN2A in human neural progenitor cells and the resultant tumors displayed the histology of malignant astrocytomas." (PMID 25785246, 2015). "To test this hypothesis, we used an orthotopic mouse model of high-grade astrocytoma that combines loss of the Cdkn2a tumor suppressor and expression of a constitutively activated form of EGFR (EGFRvIII)." (PMID 25008045, 2014). "Patients with astrocytoma and hemizygous CDKN2A/B deletion had shorter overall survival compared to patients with intact CDKN2A/B status (5.8 years vs 11.4 years, P = .04)." (PMID 42109834, 2026). "Moreover, mismatch repair deficient IDH-mutant astrocytomas are characterized by worse outcomes, and CDKN2A/B deletions may occur together with other copy number alterations in oligodendroglioma, defining the distinct subgroup of oligosarcomas linked to short survival." (PMID 39954095, 2025). "Evidence of worse survival has been reported in IDHm astrocytoma WHO grade 4 with diagnosis based upon CDKN2A/B deletion only compared to IDHm astrocytoma WHO grade 4 where diagnosis has been based upon morphology." (PMID 40392514, 2025). "Our extended molecular analysis allowed us to identify deletions in CDKN2A, which are crucial for determining the prognosis and treatment options for patients with astrocytomas." (PMID 41567539, 2025). "Despite this, 4 astrocytomas exhibited codeletion of CDKN2A/B on CNV profiling, thus carrying a far worse prognosis (CNS WHO Grade 4) than the methylation class alone would indicate (likely CNS WHO Grade 2)." (PMID 40392954, 2025). "We refine the molecular criteria for IDH1/2-mutant astrocytoma by augmenting histologic grade with hemizygous CDKN2A/B deletion and focal gene amplifications to establish three prognostically distinct tiers." (PMID 39584448, 2025). "The presence of tumor necrosis and microvascular density play a critical role in the unfavorable prognosis of patients with astrocytoma, to which is added the status of the CDKN2A gene." (PMID 40002588, 2025). "Accordingly, in astrocytomas, CDKN2A/B homozygous deletion is now recognized as a molecular criterion for grade 4 designation, even in the absence of histological markers such as necrosis or microvascular proliferation." (PMID 40507765, 2025). "IDHm astrocytoma WHO grade 4 diagnosed by simultaneous CDKN2A/B deletion and morphological criteria had a significantly worse survival than if diagnosis was based upon only one of the criteria." (PMID 40392514, 2025).
astrocytomas (continued). "Concerning the combined criteria, CDKN2A/B deletion is indeed more frequent in IDHm astrocytomas with morphological WHO grade 4 criteria compared to the morphological lower-grade astrocytomas." (PMID 40392514, 2025). "Although grade 2 or 3 tumors are stratified according to anaplasia or mitotic activity, definitive grading for CDKN2A/B-intact astrocytoma, IDH-mutant remains challenging because of differences in inter-rater consensus." (PMID 39636550, 2025). "Compared to histopathologic grade alone, the combination of CDKN2A/B loss, focal amplifications, and histopathologic grade better defined a group of IDH1/2-mutant astrocytoma patients with intermediate overall survival." (PMID 39584448, 2025). "By contrast, IDH1/2-mutant astrocytomas had a broader range of cooccurring deleterious alterations across various pathways, including between CDKN2A/B and EGFR." (PMID 39164213, 2025). "CDKN2A/B: Similar to astrocytoma, CDKN2A/B homozygous deletion is an adverse prognostic factor in grade 3 oligodendroglioma." (PMID 40949165, 2025). "Some reports indicate that in IDH-mutant astrocytoma, homozygous deletion of CDKN2A/B is a significant molecular marker for malignant transformation and is strongly associated with poor clinical outcomes." (PMID 41201287, 2025). "In patients with astrocytoma WHO grade 4 where morphological criteria were met, presence of CDKN2A/B deletion was associated with worse survival (combined subgroup)." (PMID 40392514, 2025). "The sensitivity, specificity, and positive predictive value of > 50% T2-FLAIR mismatch sign for CDKN2A-intact astrocytoma were 53.8%, 100%, and 100% (AUC = 0.769), respectively." (PMID 39117984, 2024). "In conclusion, CNS WHO grade, global DNA methylation status, and CDKN2A homozygous deletion are prognostic in patients with IDH-mutant astrocytoma." (PMID 38183430, 2024). "The 2016 WHO CNS grades of the astrocytomas that harbor CDKN2A HD were grade II in 2 tumors, grade III in 8 tumors, and grade IV in 10 tumors." (PMID 38109891, 2024). "Since homozygous CDKN2A deletion accounts for most CDKN2A mutations and has a prognosis equivalent to that of IDH-mutant astrocytoma with other CDKN2A mutations (and hemizygous CDKN2A loss), it can be used as a surrogate marker for determining prognosis." (PMID 39457569, 2024). "As such, the presence of CDKN2A/B homozygous deletion in an IDH-mutant astrocytoma of any grade upgrades the tumor to a grade IV." (PMID 39361075, 2024). "The sensitivity, specificity, and positive predictive value of > 33% T2-FLAIR mismatch sign for CDKN2A-intact astrocytoma were 88.5%, 100%, and 100% (AUC = 0.942), respectively." (PMID 39117984, 2024). "Within IDH mutant astrocytomas, global DNA methylation status and CDKN2A homozygous deletion were found to be significant prognostic indicators." (PMID 39596840, 2024). "Some reports have suggested that postoperative irradiation increases the risk of CDKN2A homozygous deletion, which is frequently observed in recurrent grade 4 IDH-mutant astrocytomas and is associated with increased cellular proliferation." (PMID 39457569, 2024). "Several recent studies also confirm the present of copy number alterations, particularly CDKN2A/B loss and CDK4 amplification, clinically conferring poorer prognosis in IDH-mutant astrocytomas." (PMID 39876890, 2024). "CDKN2A heterozygous deletion was found in 3 of 88 astrocytomas (3.4%) while 3 cases (3.4%) showed CDKN2A amplification." (PMID 38109891, 2024). "Homozygous deletion of CDKN2A is per definition restricted to IDH-mutant astrocytomas of CNS WHO grade 4 where it has been detected in 20–40% of tumors." (PMID 38183430, 2024). "This provided the basis for assigning CDKN2A/B homozygous deletions of the same grade 4 as GBM in the latest brain tumor classification for IDH-mutant astrocytoma." (PMID 38473369, 2024).
astrocytomas (continued). "Among patients with CNS WHO grade 4 astrocytoma, median overall survival was 5.5 years (95% CI 4.3–6.7) without (n = 58) versus 1.8 years (95% CI 0–4.1) with (n = 12) homozygous CDKN2A deletion." (PMID 38183430, 2024). "In this study, we investigated the association between T2-FLAIR mismatch sign and CDKN2A status among non-enhancing astrocytoma, IDH-mutant, and found that T2-FLAIR mismatch sign was correlated with CDKN2A-intact astrocytoma." (PMID 39117984, 2024). "The locations of CDKN2A-intact astrocytoma were frontal lobe in 16 cases, temporal lobe in 7 cases, insula in 2 cases, and occipital lobe in 1 case." (PMID 39117984, 2024). "In astrocytomas, 20 (22.7%) of 88 cases had CDKN2A HD, while 5 (7%) of 71 oligodendrogliomas showed this deletion." (PMID 38109891, 2024). "According to the 2021 World Health Organization classification of brain tumors, astrocytomas containing a CDKN2A/B homozygous deletion (HD) are designated as grade 4 even when no microvascular proliferation and/or necrosis is present." (PMID 38109891, 2024). "The current WHO classification recommends testing for CDKN2A/B homozygous deletion in IDH-mut astrocytomas that exhibit anaplastic characteristics of CNS WHO grade 3." (PMID 39593128, 2024). "Several clinical, molecular, and pathological prognostic factors for patients with IDH-mutant astrocytoma have been identified, including age, tumor size, primary tumor site, surgical outcome, mitotic index, and CDKN2A/B homozygous deletion." (PMID 38995493, 2024). "CDKN2A/B (Cyclin Dependent Kinase Inhibitor) homozygous deletion emerges as an independent prognostic marker in all grades of IDH-mutant astrocytomas, including grade 4 astrocytoma." (PMID 39375809, 2024). "The pathological grade of CDKN2A-HD astrocytoma based on WHO 2016 was grade II in 2 cases and grade III in 3 cases." (PMID 39117984, 2024). "Grade 4 IDH-mutant astrocytomas are defined by the presence of microvascular proliferation, necrosis, and/or homozygous deletion of cyclin-dependent kinase inhibitor 2A/B (CDKN2A/B) in IDH-mutant astrocytoma." (PMID 36765553, 2023). "This is compounded by CDKN2A/B homozygous deletion being known to occur in only a minority of IDH-mutant astrocytomas — about 0–12% of histological grade 2 tumours and 6–20% of grade 3." (PMID 37316586, 2023). "Two primary astrocytomas had a CDKN2A/B homozygous deletion and this alteration was maintained upon recurrence whereas another seven primary astrocytomas acquired CDKN2A/B homozygous deletions over time." (PMID 36739454, 2023). "While there is strong evidence to support the use of CDKN2A/B HD in grading IDH-mutant astrocytomas, several conflicting reports have been published." (PMID 37504251, 2023). "Of these IDH-mutant astrocytoma cases, two characterized by lower-grade histologic features were reclassified as grade 4 astrocytoma due to the presence of CDKN2A/B homozygous deletion, while six displayed grade 4 histology." (PMID 37741941, 2023).